CD4 (CD4 molecule)
Diseases named in the same sentence as CD4 in open-access papers (continued):
Sharing a sentence is not in itself a finding about the gene and the disease.
tumor (continued). "This is consistent with a previous study that also showed significantly higher CD8+ T cell infiltrations than CD4+ T cells in tumor-bearing mice after treatment with Salmonella." (PMID 31878272, 2019). "Our unpublished observations also indicate higher levels of PD-1 expression on CTLA + CD4 + cells in patients with a higher tumor burden." (PMID 31554169, 2019). "Myeloid-derived suppressor cells (MDSCs), regulatory T-cells (Treg/CD4+CD25+FOXP3+), and tumor-associated macrophages (TAMs) are tumor-modified immune cells that hinder the clearance of cancer cells locally and even in distant organs." (PMID 31769418, 2019). "When Tregs were depleted using Foxp3DTR mice, the cDC2s were able to better activate CD4+ T cells in the tumour and generate anti-tumour responses." (PMID 31091774, 2019). "Immunohistochemistry showed a decrease in the number of tumor-infiltrating CD8+ T cells in CD4KO mice and fewer tumor-infiltrating CD4+ T cells in tumors in CD8KO mice as compared with tumors in B6 animals." (PMID 31112530, 2019). "ELISA analysis was used to measure IFN-γ levels after 72 h co-culture of CD4+CD25+ T cells from tumor-bearing mice on control or SM16 diet with CD4+CD25− T cells from naive donors." (PMID 31288845, 2019). "It has been well established that CD4+ T lymphocytes are able to recognize cancer antigens, and that activated M1-macrophages have displayed anti-tumor functions." (PMID 30661062, 2019). "Taken together, these studies demonstrate that generating the formation of a long-lived, functional “memory-like” CD4+ T cell compartment can provide anti-tumor immunity." (PMID 31379821, 2019). "In the spleen, the percentages of effector T cells, such as CD8+ T cells and CD4+ T cells, were increased, while the percentages of two subsets of MDSCs were decreased by oxaliplatin treatment in tumor‐bearing mice." (PMID 30592157, 2019). "The efficacy of a pVAX2 DNA vaccine encoding one CD4 and one CD8 epitope in the VSV-G sequence has been validated in different tumor models, including B16F10 melanoma." (PMID 31291991, 2019). "Lung tumor cells and tumor-infiltrating antigen-presenting cells express PD-L1, which, by interacting with PD-1 on T cells, can inactivate the effector functions of both CD4+ Th1 T cells and CD8+ CTLs, leading to the evasion of antitumor immune responses." (PMID 30972427, 2019). "In regard to T-cell responses, injection of attenuated Salmonella species resulted in increased Th1 phenotype CD4 T cells in tumor infiltrates, slower tumor growth, and improved host survival in mice." (PMID 31131086, 2019). "As IL-35 is increased in the TU lung region, these results indicate an immunosuppressive function of IL-35 on anti-tumour CD4+ T cell-mediated immune responses." (PMID 30956278, 2019). "Class I or class II HER2-DC1 vaccinated mice generated anti-HER2 CD8 or CD4+ T cell immune responses and demonstrated delayed tumor growth." (PMID 31475002, 2019). "Increased IL-10+ B cell numbers in tumor tissues can also be accompanied by increased numbers of CD4+CD25+/highCD127low/− and Foxp3+ Tregs9–12, which are independently associated with tumor progression or reduced patient survival." (PMID 31519915, 2019). "A previous report demonstrated that ipilimumab treatment increases expression of ICOS on conventional CD4+ T cells in both blood and tumor tissue in patients with bladder cancer." (PMID 31192215, 2019). "We demonstrate non-uniform in vivo expansion of functional epitope-specific CD8+ and CD4+ T-cells recognizing viral antigens expressed within the PTLD tumor cells." (PMID 31736946, 2019). "PCI-based CTL vaccination was also tested in a therapeutic setting of tumor-bearing mice, including that of CD4 T-cell-depleted mice." (PMID 31333674, 2019). "The increased frequency of IFN-γ-expressing CD4+ T cells (Th1 cells) can enhance the anti-tumor function." (PMID 31387637, 2019).
tumor (continued). "CD4/Treg ratio correlated with early tumor response with a clear trend (OR 0.25, 95% CI 0.06–1.05; P = 0.059)." (PMID 30971280, 2019). "Anti-CD40/CpG activate innate immunity, mainly macrophages, while anti-CTLA-4 releases the brakes on effector T cells and can deplete CD4+ Tregs in the tumor microenvironment." (PMID 31810498, 2019). "The vascular protocol herein described presented higher CD4+/CD8+ T cells ratio within the first hours after tumour irradiation." (PMID 31906092, 2019). "Analysis of the T cell receptor (TCR)-Vβ-repertoire revealed that a polyclonal, diverse CD4+ T cell response was induced, suggesting the capacity of vaccine-activated CD4+ T cells to target multiple tumor (neo)antigens." (PMID 30956760, 2019). "This review discusses how tumor-derived vesicles are involved in the immuneresponse regulation and affect the function of CD4+/CD8+T cells in the context of a tumor microenvironment." (PMID 31993233, 2019). "The anti-tumor immune response against neoantigens that are expressed by solid tumors is predominantly attributed to MHC-I-restricted CD8 cytotoxic T cells, but MHC-II-restricted CD4 T cells are also important drivers of anti-tumor immunity." (PMID 31221199, 2019). "Namely, glycopeptides targeting DC-SIGN in DCs are easily internalized and cross-presented to stimulate tumor-specific CD4+ and CD8+ T cell responses." (PMID 31157165, 2019). "Individual HSPs or autologous tumor–antigenic peptides alone lack the ability to elicit an immune response; only HSPPCs can be endocytosed by APCs and activate CD4+ and CD8+ T cells, triggering an adaptive immune response against autologous tumor peptides." (PMID 31752169, 2019). "Enforcing local expression of XCR1 at the tumor site results in increased CD4+ T cell, CD8+ T cell and neutrophil infiltration and eradication of established tumors." (PMID 30979057, 2019). "Total CD4+ T cells constitute 20% of tumor infiltrating CD45+ leukocytes, whereas CD8+ cytotoxic T cells contribute only 5% of the leukocyte population." (PMID 30832732, 2019). "The distribution of tumor-infiltrated immune cells, such as CD4, CD8 T cells, NK (natural killer) cells, NK T cells, macrophages, granulocytes and dendritic cells, was similar between tumors generated by MC38-vector and MC38-TREM2+DAP12 cells." (PMID 31489935, 2019). "In summary, we have identified a unique tumor antigen-specific CD4+CD8+ T-cell subset which expresses a CD8-independent tumor antigen-specific TCR." (PMID 30626427, 2019). "Multivariate analysis revealed that a high density of CD4+ T cells (P = 0.005; HR<0.001, 95% CI <0.001 to 0.28) and a high density of Foxp3+ cells (P = 0.003; HR<0.001, 95% CI NA) in tumor tissues were strongly correlated with better progression-free survival." (PMID 30978241, 2019). "Overall, we predominantly observed increased PMN-MDSC populations with increased tumor weight in blood, spleen and tumor, whereas blood CD4+ T cells as well as tumor-resident NK cells decreased." (PMID 31694706, 2019). "Most of the tumor-infiltrating CD4+CD25+ cells expressed FoxP3, and their proportion was 2-fold higher in DC-specific Dll1−/− mice compared to wild-type littermates." (PMID 30940183, 2019). "Using whole lysates of either autologous or allogeneic tumor cells can lead to the presentation of multiple epitopes for a prolonged period, enabling longer antigen presentation that will allow both CD4 and CD8 T-cell responses." (PMID 31131086, 2019). "Flow cytometric analysis of freshly prepared tumor cell suspensions revealed increased intracellular ratios of IFN-γ to IL-4 in CD4+ and CD8+ memory T cells, and activation of tumor-associated myeloid cells and microglia with upregulation of HLA-DR and PD-L1." (PMID 30506500, 2019). "An obvious increase in DCs recruitment, tumor-infiltrating CTL (CD4+ and CD8+) as well as a significant decrease in Treg cells was observed when immunotherapy combined with PDT." (PMID 31754376, 2019).
tumor (continued). "CD4+ T cells can also become directly cytolytic to tumor cells, for example via tumor necrosis factor (TNF)-related apoptosis-inducing ligand (TRAIL) or Fas/Fas ligand (FasL) pathways." (PMID 30956760, 2019). "In mouse spleens infected with Salmonella enterica serovar Typhimurium, analysis of Tregs characterized by CD4+ CD25hi CD127low revealed that the decrease in tumor growth depended on lipopolysaccharides and lipoproteins." (PMID 31635338, 2019). "We suggest the efficacy of this treatment is due to the fact that CD4 T cell depletion switches the anti-tumor response from a Th2 or Th1/Th2 toward a Th1 mode, as anticipated on the threshold mechanism." (PMID 31231378, 2019). "The growth of primary tumours and metastases is strongly inhibited in C3-deficient mice and is associated with increased numbers of IFNγ+/TNFα+/IL10+ CD4+ and CD8+ T cells." (PMID 30841875, 2019). "In contrast, the Tbethi Tregs do infiltrate the tumor cell nests and their number strongly correlated with that of tumor-infiltrating Tbet+ CD4+ and CD8+ effector T cells as well as with the detection of ongoing HPV-specific type 1 T cell responses." (PMID 30658697, 2019). "We observed that the frequency of CD4+Foxp3+ Tregs was significantly increased in the populations of circuiting and tumor-infiltrating T cells from BC patients compared with those from healthy donors, as demonstrated by flow cytometry (P < 0.05)." (PMID 30718502, 2019). "According to report, CD4+T cells can be detected in both nsPEFs treated tumor and untreated secondary transplantation tumor." (PMID 31256187, 2019). "Specifically, alemtuzumab has been assessed for CD4-CAR T cell elimination following tumor cell eradication in NSG mice to prevent T cell aplasia." (PMID 31884955, 2019). "Likely, both components of adaptive immune response can play a role at different stages of tumor formation, and the ability of balanced induction of both CD4+ and CD8+ T cells is an advantageous feature of the GAd vaccination platform." (PMID 31217437, 2019). "The densities of CD8+ T cells and CD4+ T cells among tumour infiltrating lymphocytes (TILs) before CRT have been suggested to predict pathologic tumour response in rectal cancer." (PMID 29765096, 2018). "Among CD45+ tumor cells, anti PD-1 treatment significantly increased the frequency of effector CD4+ T cells." (PMID 30117062, 2018). "Further dissection of the relative contribution of CD4 versus CD8 cells to the MIF-dependent immune-mediated control of tumor growth will be of interest in future studies." (PMID 29864117, 2018). "The data above show that the antitumor response induced by intratumor treatment with mRNA encoding MLKL can lead to priming of tumor xeno-antigen-specific CD8+ and CD4+ T cells and to the elimination of cells that display this antigen." (PMID 30143632, 2018). "The tumor cells in PCALCL possess an activated T-cell phenotype and express CD2, CD4, and CD45RO, with a loss of CD2 and CD5 occurring variably." (PMID 29915722, 2018). "Immune checkpoint markers, including expression of CTLA-4, TIM3, and Ox40 on CD8+ and CD4+ T cells were examined in the tumor draining lymph node and spleen." (PMID 29844427, 2018). "Quantification of representative tumor images confirmed that there was a significant increase of CD4+ immune cells in IL-12-LNP-treated mice." (PMID 30458889, 2018). "Immunohistochemical analysis of the SC mts revealed a 10-fold increase of CD8+ lymphocytes with respect to the primary tumor; less so (3-fold) for CD4+ cells." (PMID 29774030, 2018). "In particular, high density of CD8+ and/or CD4+ T cells in tumor stroma were independent favorable prognostic factors for NSCLC." (PMID 30409126, 2018). "CD4+ TIL from four additional patients displayed robust IFN-gamma production in response to DC loaded with autologous tumor." (PMID 30400835, 2018).
tumor (continued). "In G2, CD4+ T cells were positively correlated with the mitosis percentage (p ≤ 0.05, r = 0.884), and tumor growth rate (p ≤ 0.05, r = 0.966), suggesting prevalence of Tregs." (PMID 29755647, 2018). "For example, tumor-derived exosomes are capable of inducing expansion of CD4+CD25+Foxp3+ Treg cells and their suppressor activity, and to trigger CD8+T cells apoptosis." (PMID 29515996, 2018). "CD4+ T cell lineage commitment was found to be more pronounced in tumour-infiltrating lymphocytes (TILs) compared to PBMC and regional lymph nodes, indicating that differences in the tissue environments have a significant impact on CD4+ T cell destiny." (PMID 30075815, 2018). "As in mice, immunosuppressive functions were associated with CD4+ iNKT cells in various tumor settings, further implicating a functional distinction between CD4+ and CD4− iNKT populations." (PMID 29973936, 2018). "In our study, G1 showed the lowest CTL/B ratio suggestive of Breg predominance and a high number of CD4+ T cells, which were related to the tumor expansion observed." (PMID 29755647, 2018). "Tumor regression was abrogated by depletion of CD8+ T cells, but depletion of CD4+ T cells improved the anti-tumor effects of IL PV-10 therapy." (PMID 29694419, 2018). "Aberrant expression by H-RS cells of surface molecule PD-L1, the ligand for PD- expressed on CTLs and CD4+ T cells, reduces anti-tumor immune function by T cell exhaustion." (PMID 30101129, 2018). "Depletion of Tregs was equally as effective as CD4+ T cell depletion at enhancing the anti-tumor immunity induced by combination therapy with IL PV-10 and anti-PD-1 antibodies (p<0.05 compared to all other treatment groups)." (PMID 29694419, 2018). "In line with our data, a recent report has shown that TIL fragments derived from small pieces of the patient's tumor contain more CD4+ T cells than CD8+ T cells (19/24 TIL fragments)." (PMID 30233577, 2018). "To better understand the mechanism behind the pIL-12 GET induced tumor regression, we evaluated CD4+ and CD8+ T cell memory phenotype status in peripheral blood at different time points." (PMID 30544810, 2018). "IFN-γ activates expression of MHCII and co-stimulatory molecules in the antigen presenting cells, and promote the Th1 differentiation of CD4+ T cells to increase immunogenicity of tumor cells." (PMID 30166607, 2018). "To confirm the predominant role of the TdLN in the induction of tolerance by the tumor, we set up a model where Ag-specific CD4+ T cells are immunized in a distant LN (popliteal) by f.p. immunization with DBY+CpG in incomplete Freund's adjuvant (IFA)." (PMID 29844317, 2018). "Understanding CD4 TRM flexibility during chronic infection or within the tumor microenvironment will also be important for assessing the potential of vaccines to target these populations." (PMID 30386342, 2018). "IL-12 has been previously shown to induce anti-tumor immune surveillance through the recruitment of host immune cells such as CD3+ CD4+ helper T-lymphocytes." (PMID 30458889, 2018). "Recent studies point to an expanded role of CD4+ T cells in anti-tumor immunity, warranting further investigation into the function and potential efficacy of this underexplored TIL population." (PMID 30400835, 2018). "We demonstrate that TILs have a high degree of CD4+ T cells with lineage commitment, proposing an active immune response towards the tumour." (PMID 30075815, 2018). "In this study, B-9-3 in both standard and tumor-bearing mice reduced the number of CD4+CD25+FOXP3+ regulatory T cells in both the blood and in the spleen." (PMID 30079021, 2018). "Venus+ CD4+ T-cells were detected in the tumor, but to a lesser extent than CD8+ T-cells; more venus+ CD4+ T-cells were detected in the tumors of mice treated with anti-PD-1 or anti-CTLA-4 mAb than in the other groups." (PMID 29348598, 2018).
tumor (continued). "JTX-2011 is a first-in-class ICOS agonist antibody that has been demonstrated preclinically to have a tumor-centric dual mechanism of action through stimulation of CD4 T effector cells and depletion of intratumoral T regulatory cells." (PMID 30400835, 2018). "Since IFN-γ is crucial for anti-tumor reactivity, phenotypic analyses were conducted to determine how the absence in IL-23 signaling affected CD4+ or CD8+ cell expression of IFN-γ during the course of lesion development and progression." (PMID 29664967, 2018). "Evidence suggesting that CD8+, CD4+, and macrophages effector cells were actually killing tumor cells was obtained, supported by ISNT and GZMB expression." (PMID 29774030, 2018). "In previous studies, we discovered that both human CD4+CD25hiFoxP3+ naturally occurring Treg (nTreg) and tumor-derived γδ Treg cells induce responder T-cell senescence as a suppressive mechanism." (PMID 29339767, 2018). "Our data indicated the importance of activation of TAA-specific CD4+ helper T cells in tumor immunity." (PMID 30542516, 2018). "Consistently, our previous studies demonstrated that BTLA expression significantly increased on tumor-infiltrating CD4+ T cells which suppressed cytokine production in HCC patients." (PMID 30116751, 2018). "In contrast, the 30 mg/kg dose achieved near maximal occupancy on all cell types assayed, with 87, 85, and 84 percent occupancy detected on splenic CD4+ T cells, tumor cells, and tumor-infiltrating CD4+ T cells, respectively." (PMID 30133535, 2018). "We found that in addition to CD8+ cells and a singular case of constitutive tumor cell expression, PD-1 was frequently expressed on CD4+ effector cells, Tregs, and occasional CD20+ B-cells." (PMID 30285852, 2018). "CD8 and CD4 T-cells can be detected against tumour specific phosphopeptides but these have yet to prove efficacy in a clinical setting due to the instability of the phosphorylated peptides." (PMID 29570634, 2018). "Instead, these CD4+ T cells are driven toward anergy or peripherally-induced Treg (pTreg) differentiation, from the early stage of tumor development." (PMID 29844317, 2018). "Our data demonstrate that our proprietary algorithms accurately predict tumor specific neoepitopes, which appropriately engender CD4+ and CD8+ T cell responses." (PMID 30400835, 2018). "Consistently, Church and colleagues demonstrated that tumor-specific CD4 T cells help to maintain functionality of tumor-directed CD8 T cells." (PMID 29032503, 2018). "HOE642 + anti-PD-1 combination therapy reduced the CD4+ Treg cell counts while increased tumor infiltration of CD4+IFNγ+ T cells and CD8+ IFNγ+ T cells in GL26 tumors." (PMID 30333031, 2018). "Overall, the Inter-Organ Clone Tracking analysis revealed that anti-CD4 mAb treatment enhances the mobilization of a wide variety of tumor-reactive CD8+ T cell clones into the Cancer-Immunity Cycle and thus induces a robust antitumor immune response in mice." (PMID 30733724, 2018). "Cytokine release and T cell proliferation was most effective when tumor cells simultaneously encountered genetically engineered CD4+ and CD8+ T cells." (PMID 30214445, 2018). "Adoptive transfer of in vitro expanded tumor-specific autologous CD4+ T cells can induce long-term complete remission in cancer patients." (PMID 29844317, 2018). "Consistent with a role of T cells in tumor rejection, we found infiltrated CD4+ and CD8+ T cells 14 days after injection in C57Bl6 mice." (PMID 29930552, 2018). "Less than 1% CD8+ T cells infiltrating in parenchyma and meanwhile less than 10% CD8+ T cells (8% for CD4+ cells) infiltrating in mesenchyme were defined as a poor infiltration in total tumor area; the others were regarded as a rich infiltration." (PMID 30285868, 2018). "Example high power fields of the T cell panel (CD8+ T cells, CD4+ T cells and Treg) are shown for the tumor margin (TM), intra-tumor (IT) and peri-tumoral (stroma) regions in patients MelTIL026 and MelTIL015." (PMID 30042403, 2018).